CD86 (CD86 molecule)
Diseases named in the same sentence as CD86 in open-access papers (continued):
Sharing a sentence is not in itself a finding about the gene and the disease.
osteosarcoma (8 papers, 2015 to 2025). A usually aggressive malignant bone-forming mesenchymal neoplasm, predominantly affecting adolescents and young adults. "In support of this result, a biomarker experiment study showed that the CD86/CD28 stimulatory pathway associated with activated memory CD4 T cells was dominant in osteosarcoma patients with a good prognosis." (PMID 39081321, 2024). "In this study, CD86 expression was significantly correlated with naïve B cells and M2 macrophages, and M0 and M2 macrophages were the major constituents of TIICs in osteosarcoma." (PMID 35463956, 2022). "Combining these results, we deduced that the CD86/CD28 stimulatory pathway was dominant in osteosarcoma patients with a good prognosis." (PMID 35463956, 2022). "In conclusion, these findings help us better understand the prognostic roles of IRGs and TIICs in osteosarcoma, and CD86 and PGF may serve as specific immune targets." (PMID 35463956, 2022). "Thus, blocking CD86/CTLA4 signaling and promoting CD86/CD28 signaling are potential strategies for osteosarcoma immunotherapy." (PMID 35463956, 2022). "More studies are needed to further explore the role and mechanism of PGF and CD86 in osteosarcoma." (PMID 35463956, 2022). "Though the exact function of expression of CTLA-4 on tumor cells is unknown, incubating the cells with CTLA-4 ligands CD80 or CD86 induced apoptosis in human osteosarcoma cell line HOS cells through caspase-3 and caspase-8 activation." (PMID 33823818, 2021). "Moreover, CD80 and CD86 expression on metastatic osteosarcoma was significantly increased after α-PD-L1 mAb treatment suggesting that tumor cells may be directly or indirectly using this pathway to suppress CTL-mediated killing." (PMID 25992292, 2015). "The upregulation of immune-related genes such as CD86, FCER1G, and ITGAM suggests involvement of immune activation and inflammatory signaling within the osteosarcoma microenvironment." (PMID 40895569, 2025). "Therefore, CD86 may be mainly expressed in M2 macrophages in osteosarcoma." (PMID 35463956, 2022). "In this study, CD86 expression was significantly correlated with CTLA4 and CD28 expression in osteosarcoma." (PMID 35463956, 2022). "In summary, blocking CD86/CTLA4 signaling and promoting CD86/CD28 signaling are potential strategies for osteosarcoma immunotherapy." (PMID 35463956, 2022). "In the TARGET osteosarcoma cohort, IL18 expression was positively correlated with M1 marker CD80 and CD86 and M1 abundance in tumor-infiltrating immune cells." (PMID 36274066, 2022). "Therefore, we concluded that CD8 activation by T-cells was directly prevented by the CD86/CTLA4 coinhibitory signal and was indirectly inhibited by Tregs in osteosarcoma." (PMID 35463956, 2022). "Finally, our results showed that CD86 and PGF may serve as potential specific immune targets for osteosarcoma." (PMID 35463956, 2022). "Our results showed that CD86 mRNA expression in tumor tissues was higher than that in normal bone tissues, and elevated CD86 expression was beneficial to the prognosis of osteosarcoma." (PMID 35463956, 2022). "Moreover, CD86 expression depended on its receptors, CTLA4 and CD28, in osteosarcoma." (PMID 35463956, 2022). "CD86 signaling and PGF may serve as potential specific immune targets in osteosarcoma." (PMID 35463956, 2022). "To determine if T cell responses to osteosarcoma metastatses in α-PD-L1 mAb treated mice may have become tolerized through engagement of other inhibitory ligands, we evaluated expression of PD-L1, CD80, and CD86 on metastatic osteosarcoma cells, in both mock treated and α-PD-L1 mAb treated mice." (PMID 25992292, 2015).
parasitemia (8 papers, 2013 to 2024). "Increased parasitemia during peak infection was associated with increased cell frequency and expression of CD38, ICOS and CD86 by Vδ2+ T cells and increased CD86 and HLA-DR by Vδ1+ T cells." (PMID 37968278, 2023). "DCs recruited to the peritoneum also showed an up-regulation of the co-stimulatory molecules CD80 and CD86, suggesting that these DCs acquire a semi-mature phenotype upon parasite infection." (PMID 26720149, 2015). "In contrast, CD86 blockade or dual blockade of CD80 and CD86 resulted in the inability of mice to clear parasitemia to sub-patent levels." (PMID 30631323, 2018). "It is likely that the parasitic infection does not impair the expression of CD86 in the APCs because the up-regulation of CD86 in the APCs was observed in the infected groups." (PMID 23555767, 2013). "iRBC- and TLR1/2 and TLR4 agonist-induced CD86 expression was also lower in CD1c+ cells isolated at peak parasitemia than prior to infection, while there was no change in TLR1/2 and TLR4-induced IL-12 expression and all three stimuli, iRBCs, TLR1/2 and TLR4 agonists, increased intracellular TNF." (PMID 31900030, 2020).
neuroblastoma (7 papers, 2003 to 2023). Neuroblastoma (NB) is the most common solid, extracranial childhood tumor. "Research shows that CD86 induced a T-cell immune response in neuroblastoma in vitro and served as an effective tumor vaccine in the tumor prevention model." (PMID 37479876, 2023). "We have developed a cell-based vaccine that features the expression of both CD80 and CD86 on the surface of a murine neuroblastoma cell line." (PMID 17397536, 2007). "However, we also found a chemotherapy-dependent induction of the checkpoint ligand expression on neuroblastoma, namely PD-L1, CD86, CD155, and Gal-9 (up to 5-fold increase vs. control)." (PMID 36765861, 2023). "We investigated chemotherapy effects on the expression of PD-L1 (PD-1), CD86 (CTLA-4), CD155 (TIGIT), and Gal-9 (TIM-3) immune checkpoint ligands by neuroblastoma cells." (PMID 36765861, 2023). "Ewing sarcoma cDCs showed significantly lower percentages of CD83-, CD86-, and TNFSF9-expressing cells and Ewing sarcoma Mφ had significantly lower CD70-, CD80-, CD83-, and TNFSF9-expressing cells, than neuroblastoma." (PMID 37823774, 2023). "In monocytes co-cultured in the presence of neuroblastoma cells, the CSF-1R inhibitor BLZ945 partially restored HLA-DR and CD86 expression and reduced the immunosuppressive capacities of the monocytes on T cell proliferation." (PMID 31191529, 2019). "CD80 and CD86 are critical to the function of T cells and are not typically present on the surface of neuroblastoma cells." (PMID 35326601, 2022). "Here, we have investigated the expression of costimulatory molecules (CD40, CD80, CD86, PD-1L, B7H2, OX40L and 4-1BBL) in human neuroblastoma (NB) cells, since virtually no information is available on this issue." (PMID 12771917, 2003).
pulmonary fibrosis (7 papers, 2017 to 2024). Chronic progressive interstitial lung disorder characterized by the replacement of the lung tissue by connective tissue, leading to progressive dyspnea, respiratory failure, or right heart failure. "We assess not only the correlation between MSR1- or CD86-expressed macrophages and clinicopathological factors of lung fibrosis but also its influence on the survival after lung transplantation." (PMID 33604393, 2021). "Our study identified increased expression of many exosomal surface epitopes (CD19, CD8, CD69, and CD86) in IPF patients with respect to controls, suggesting that an alteration of these markers may be associated with lung fibrosis." (PMID 33925174, 2021). "However, studies in a bleomycin model of pulmonary fibrosis by Soler’s group demonstrated a sustained increase in CD11c+/MHC II+ dendritic cells and increased expression of MHC II and CD86 throughout the fibrotic stage of bleomycin-induced disease." (PMID 28700752, 2017). "Our studies have shown increased deposition of collagen with silica-induced pulmonary fibrosis, which is concurrent with the increased percentage of the CD11b+CD11c+ subset of CFPs expressing CD80/CD86, suggesting that DDR2/collagen I signaling may play a role in activation of the immune CFP subset." (PMID 28700752, 2017). "Given the number of CD206 + macrophages, but not CD163+, CD68+, CD86+ or iNOS+ macrophages, was markedly decreased upon microcystin-LR treatment, it was reasonable to assume that microcystin-LR could meliorate pulmonary fibrosis mainly by suppressing CD206+ M2a-like macrophage differentiation." (PMID 32075954, 2020).
sarcoidosis (7 papers, 2012 to 2025). Sarcoidosis is a multisystemic disorder of unknown cause characterized by the formation of immune granulomas in involved organs. "CD86 and COL5 showed a similar expression in both IPF and sarcoidosis lungs while COL6 was enhanced in IPF lungs." (PMID 35203313, 2022).
type 1 diabetes (7 papers, 2011 to 2025). "Notably, the experimentally validated CD86 (M2) had many associations with immune disease terms (C4), such as type I diabetes mellitus or autoimmune thyroid disease." (PMID 40593564, 2025). "One of the notable characteristics of the DC generated from monocytic progenitors in the presence of the mixture of antisense DNA targeting the primary transcripts of CD40, CD80, and CD86 used in the phase I type 1 diabetes safety trial is their ability to produce retinoic acid (RA)." (PMID 29774025, 2018).
abortion (6 papers, 2014 to 2025). the ending of pregnancy by removing a fetus or embryo before it can survive outside the uterus. "In cDC cells, CD62L-HLA DR++ monocyte %monocyte and CD86 on granulocyte were positively associated with abortion (OR > 1)." (PMID 39388432, 2024). "A higher M1/M2 ratio of dMφs was demonstrated in spontaneous abortion, which manifested a higher expression of M1-associated markers (CD86, CD80, and IL-1β) and lower expression of M2-associated markers (CD209, CD206, IL-10, and TGF-β1." (PMID 37033974, 2023). "CD86+ cells in the placentas of the abortion group were significantly more abundant than in the normal group, whereas anti-CXCL9 treatment notably reversed this effect." (PMID 41280905, 2025). "DC AC, CD62L-DC AC, CD62L-DC %DC, CD86+ myeloid DC AC and CD62L-myeloid DC AC were negatively associated with abortion (OR < 1)." (PMID 39388432, 2024). "In the context of pregnancy, the blockade of CD80 and CD86 molecules in early stages of gestation abortion-prone mice (CBA/JxDBA/2) increased production of Th2 cytokines and frequency of Treg cells and decreased the fetal resorption." (PMID 24771983, 2014). "Furthermore, the systemic inhibition of CD80 and CD86 at the implantation period of pregnancy inhibited the rejection of fetuses in abortion-prone mice." (PMID 34298914, 2021).
allergic asthma (6 papers, 2014 to 2025). A asthma with a basis in a pathological type I hypersensitivity reaction. "Given the key roles of MHC class II and CD86 in T cell activation and to get further insights into the development of allergic inflammation, we asked whether March1 deficiency exacerbates or attenuates features of allergic asthma in mice." (PMID 29854835, 2018). "This study found that in children with acute exacerbations of allergic asthma, there is an enhanced polarization of macrophages towards the M2 phenotype, characterized by decreased expression of CD86 and increased expression of CD206." (PMID 40260311, 2025). "Thus, one possibility to investigate in the future is that the increased expression of both MHCII and CD86 in March1-deficient mice blunts the Th2 response to the allergen and/or activates Th17 cells, which are known to increase neutrophil influx in airways of mice with allergic asthma." (PMID 29854835, 2018). "In addition, CD86 siRNA treatment did not stimulate systemic production of IL-6 or IFN-β, suggesting that CD86 may become a promising target for the treatment of allergic asthma." (PMID 25344652, 2014). "CD86 and CD206 are key markers that distinguish between M1 and M2 macrophages, and their expression is markedly increased in allergic asthma." (PMID 38646478, 2024). "Our findings showed that IgE-hFcεRI-dependent upregulation of co-stimulatory CD80, CD86, and CD40 on hFcεRI eosinophils would be consonant with a recent study of 32 allergic asthma subjects who had clinically beneficial responses over 16 weeks of treatment with the anti-IgE mAb, omalizumab." (PMID 39996772, 2025). "Flow cytometry results showed that the proportion of M1 (CD86+) and M2 (CD206+) macrophages was decreased in OVA-induced allergic asthma mice with 3-BP intervention, whereas they increased in OVA-sensitized and challenged mice with S100A9 overexpression (p < 0.01)." (PMID 38646478, 2024).
colorectal tumor (6 papers, 1998 to 2025). "Treatment with IR780+L in colorectal tumor‐bearing mice elevated the proportion of mature DCs, characterized by CD80+ and CD86+ expression in CD11c+ DCs." (PMID 39525955, 2024). "The lack of CD70, CD80, or CD86 expression on ILCs in colorectal tumors could, therefore, be the consequence of signals counteracting the effect of inflammasome-associated cytokines in the local microenvironment." (PMID 32341343, 2020). "The absence of autologous tumour-specific cytolytic T-cell (CTL) activity may be due to the poor immunogenicity of colorectal tumour cells, which we found expressed only low levels of MHC I antigens and CD54 and failed to express MHC II antigens or the co-stimulatory molecules CD80, CD86 or CD106." (PMID 9569042, 1998).
esophageal cancer (6 papers, 2019 to 2024). A primary or metastatic malignant neoplasm involving the esophagus. "In the published studies of esophageal cancer, CD86 is more like a positivity immune regulatory molecule." (PMID 35201503, 2021). "It has been found that the expression of CD86 on the surface of dendritic cells decreased in esophageal cancer TME." (PMID 35201503, 2021). "However, both gastric and esophageal cancers demonstrate significant decreases in promoter methylation of PDL1 and CD86 with increasing age." (PMID 34433020, 2021). "Moreover, our study indicates that EBV and cytomegalovirus elevate PD-L1 or PD-L2, CD80, CD86, PD-1, CTLA-4, Tim-3, LAG3, and 4-1BB expression in multiple cancers along the gastrointestinal tract including stomach and esophageal carcinoma and colon and rectum adenocarcinoma." (PMID 30911684, 2019).
ischemia (6 papers, 2015 to 2025). A hypoperfusion of the BLOOD through an organ or tissue caused by a PATHOLOGIC CONSTRICTION or obstruction of its BLOOD VESSELS, or an absence of BLOOD CIRCULATION. "Our research identified p21 as a more dominant marker than p16 in microglia post‐ischemia, particularly in CD86‐positive M1 microglia." (PMID 40585759, 2025). "Building on this discovery, we developed an exosome‐based senolytic therapy, Que@micro‐Exo, which effectively targets and eliminates p21+CD86+ microglia post‐ischemia." (PMID 40585759, 2025). "While MCAO mediated ischemia effectively increased the number of the Iba1+CD86+ cells, the hUC-MSC and curcumin treatment significantly decreased these pro-inflammatory phenotypes." (PMID 36829224, 2023). "Multiple microglia-related genes such as Cxcl10, Tlr7, Cd86, Tnfrsf1a, Nfkbia, Tgfb1, Ccl2 and Il-6, were upregulated with prolonged ischemia." (PMID 35154109, 2022). "In the frontal cortex and in the dorsal striatum of the animals treated with AP39 and subjected to ischemia, we observed a reduced expression of CD86, a marker of the cytotoxic M1-like phenotype of the microglia." (PMID 34360581, 2021). "However, in the cortex of the parasagittal gyrus, the ischemia-hypothermia group showed a reduced ratio of CD86 to CD206 compared with ischemia-normothermia (p = 0.001)." (PMID 35690757, 2022). "The MCAO procedure did not evoke any significant changes in the CD86 expression; however, in the group treated with AP39 and subjected to ischemia, a reduced CD86 expression was observed in the frontal cortex and in the dorsal striatum (p = 0.048 and p = 0.016, respectively)." (PMID 34360581, 2021).
myeloid leukemia (6 papers, 2014 to 2023). A clonal proliferation of myeloid cells and their precursors in the bone marrow, peripheral blood, and spleen. "While data are lacking on the expression of CD80 and CD86 in HTLV-1 infection and pathogenesis, IFN-α enhanced CD80 expression in vitro in myeloid leukemia, while IFN-β has been shown to regulate CD80 and CD86 in vivo and in vitro in MS." (PMID 24472094, 2014). "As previously demonstrated by our group, myeloid leukemia cells can provide direct costimulation via CD80, CD86, and ICOS-LG molecules, and these malignant blasts are proficient in utilizing elaborate immune evasion strategies including the adaptive resistance and T-cell exhaustion." (PMID 31406210, 2019). "Each of the assays addresses a specific activation, U937 the expression of CD86, THP1 the expression of CD86 and CD54, IL-8 the production of IL-8, and as for the last one, the measurement of the expression of more than 200 mRNAs in a cell line derived from human myeloid leukemia, SenzaCell." (PMID 35373185, 2022). "An in vivo study of murine myelogenous leukemia suggested that blockade of B7-1 (CD80) and not B7-2 (CD86) by CTLA-4 contributed to the attenuation of anti-leukemic immunity." (PMID 33669431, 2021).
non-small cell lung carcinoma (6 papers, 2019 to 2024). A group of at least three distinct histological types of lung cancer, including non-small cell squamous cell carcinoma, adenocarcinoma, and large cell carcinoma. "CD80 and CD86 are moderately expressed in some tumors, such as non-small cell lung cancer, especially on the surface of cancer cells, thus helping cancer cells to escape from the immune attack." (PMID 31440272, 2019). "It was shown to downregulate IFNγ-induced MHC-I expression in non-small cell lung cancer cell lines, and CD80/CD86 in dendritic cells stimulated with lipopolysaccharide, thereby reducing T-cell stimulatory capacity." (PMID 35655783, 2022).
pneumonia (6 papers, 2018 to 2025). An acute, acute and chronic, or chronic inflammation focally or diffusely affecting the lung parenchyma, caused by an infection in one or both of the lungs (by bacteria, viruses, fungi, or mycoplasma.). "In a study by Parker, CD80 and CD86-deficient mice displayed significant reductions in several pro-inflammatory cytokines and significantly improved survival rates in a murine model of pneumonia." (PMID 37004108, 2023).
acute lymphoblastic leukemia (5 papers, 2016 to 2025). Leukemia with an acute onset, characterized by the presence of lymphoblasts in the bone marrow and the peripheral blood. "However, in contrast to stable CD80 and/or CD86 expression on primary DLBCL cells, PD-L1 cell surface expression on pediatric B-cell precursor acute lymphoblastic leukemia (ALL) depends on induction by IFN-γ and TNF-α." (PMID 38340727, 2024).